APOB (apolipoprotein B)
Diseases named in the same sentence as APOB in open-access papers (continued):
Sharing a sentence is not in itself a finding about the gene and the disease.
dyslipidaemia (continued). "Individuals with chronic kidney disease (CKD) often present with dyslipidaemia, consisting of decreased levels of high-density lipoprotein cholesterol (HDL-C), hypertriglyceridemia, together with raised levels of ApoB and varying levels of LDL-C." (PMID 35054008, 2022). "A study of apoB kinetics after 120 mg of torcetrapib, with or without atorvastatin, which was given to subjects with dyslipidaemia, demonstrated that torcetrapib reduced LDL apoB by increasing its fractional catabolic rate (FCR)." (PMID 34849601, 2022). "Obese subjects frequently have atherogenic dyslipidaemia, including elevated sdLDL levels, in addition to elevated triglycerides (TG), very low density lipoprotein (VLDL) and apolipoprotein-B, as well as decreased high density lipoprotein cholesterol (HDL-C) levels." (PMID 23507795, 2013). "Similarly, reduced expression/activity of apoB in MR and six RCT studies resulted in genetically predicted lower levels of LDL cholesterol and total cholesterol in the UK Biobank as well as improved outcomes in the treatment of dyslipidaemias, respectively." (PMID 37751957, 2023). "In the studied groups of patients the concentration of lipids, apoAI and apoB did not change as compared to controls, but they showed a significant divergence of the tested parameters from very low to very high, which indicated dyslipidaemia and dyslipoproteinaemia in these patients." (PMID 26666260, 2015).
Abdominal obesity (41 papers, 2006 to 2025). Excessive fat around the stomach and abdomen. "ApoB is a well-established marker of atherosclerotic risk, and its association with abdominal obesity underscores the importance of evaluating fat distribution, not just total fat mass." (PMID 41373924, 2025). "Considering the central obesity indicators (waist circumference, hip circumference, waist-to-hip ratio) may have a positive or reverse causal relationship with the ApoB/ApoA1 ratio." (PMID 38310324, 2024). "Unless for TG level, the study confirmed a female gender effect on lipids, apoA and apoB levels in both sickle cell genotypes, where a similar abdominal obesity was observed, almost exclusively encountered in females." (PMID 29506549, 2018). "Studies involving postmenopausal women showed that abdominal obesity was characterized by increased CVD risk factors such as VLDL1‐TG and apoB production, hepatic fat and non‐HDL cholesterol, which has important implications for CVD risk in this group." (PMID 29040543, 2018). "As is evident from our data, there is a strong relationship between leptin, adiponectin, and abdominal obesity with increased CVD risk, as assessed by the apoB/apoA1 ratio." (PMID 16606459, 2006). "Our observation of a weak trend between the apoB/apoA-1 ratio and BC severity may reflect characteristics of the MetS such as abdominal obesity playing a role in BC development – however, experimental evidence is needed to support this hypothesis." (PMID 28376727, 2017). "People with central obesity were mainly women and had a worst cardiovascular risk profile than those without central obesity; indeed, they had higher values of glucose, HbA1c, LDL-cholesterol, apoB, systolic and diastolic blood pressure, and lower values of HDL-cholesterol and apoA1." (PMID 24788805, 2014). "These comprised lipid profiles (LDL-C, sdLDL-C, apolipoprotein B, TG/HDL-C ratio), abdominal obesity (waist circumference, total body fat, and visceral fat), uric acid levels, and HOMA-IR." (PMID 39125322, 2024). "Children with excessive weight; abdominal obesity; increased gynoid and android body fat; low HDL-c; hyperglycemia; and elevated uric acid, homocysteine, and apoB had higher chances of presenting increased hs-CRP (P < 0.05)." (PMID 31143476, 2019). "OTN in SCC and ACS, VOC and OTN in SCA were not affected by gender, BMI, BMI classes, WHR (excepted for OTN in SCC patients), abdominal obesity, TC, LDL-C, HDL-C, apoA or apoB levels or apoB/apoA ratio." (PMID 29506549, 2018).
abetalipoproteinemia (41 papers, 2006 to 2025). "MTP's requirement during apoB lipoprotein assembly was first demonstrated by linking abetalipoproteinemia with mutations in the M subunit." (PMID 22353470, 2012). "We conclude that the main feature of the MTTP p.I564T variant is impaired ApoB secretion and hepatic lipid accumulation as a result of decreased lipid transfer activity distinct from the classical abetalipoproteinaemia phenotype where MTP expression is abolished." (PMID 37484212, 2023). "Its role as an essential chaperone for the biosynthesis of apolipoprotein B (apoB)-containing triglyceride-rich lipoproteins was established after the realization that abetalipoproteinemia patients carry mutations in the MTTP gene resulting in the loss of its lipid transfer activity." (PMID 22353470, 2012). "Lipoprotein(a) assembly mechanism does not appear to be clearly elucidated, but some have suggested ApoB to be a limiting factor based on studies in subjects with abetalipoproteinemia." (PMID 39210428, 2024). "Other APOB mutations cause abetalipoproteinemia (ABL) (OMIM, 200100) and hypobetalipoproteinemia (FHBL) (OMIM, 615558), two rare, autosomal recessive disorders characterized by hypocholesterolemia and malabsorption of fat-soluble vitamins, causing neuropathy, coagulopathy, and retinal degeneration." (PMID 37510094, 2023). "Abetalipoproteinaemia (ABL) is characterized by a deficit in the low density apolipoprotein-B (VLDLs)." (PMID 20808545, 2010). "Analyses of several missense mutations causing amino acid substitutions in abetalipoproteinemia revealed that these mutants lack lipid transfer activities and do not support apoB-lipoprotein secretion." (PMID 38325741, 2024). "The best examples of this are heterozygous truncating mutations in APOB [encoding apolipoprotein B (ApoB)], causing hypobetalipoproteinaemia and biallelic mutations in MTTP (encoding microsomal triglyceride transfer protein), which cause abetalipoproteinaemia." (PMID 27899914, 2016). "Abetalipoproteinemia (ABL; OMIM 200100) is a rare autosomal recessive disease due to mutations in both alleles of the MTP gene; affected patients exhibit nearly undetectable levels of ApoB and very low plasma cholesterol levels." (PMID 25852563, 2015). "Thus, loss of Sar1B's lipoprotein secretion-promoting activity appears to impair apoB lipoprotein production, albeit to a lesser extent than the impairment that occurs in abetalipoproteinemia." (PMID 24338480, 2014). "Additionally, elevated plasma concentrations of ApoE in the HDL fraction are observed in patients with abetalipoproteinemia, suggesting that ApoE may play a significant role in lipid secretion in place of ApoB under certain pathological conditions." (PMID 40180213, 2025). "Just recently, Hendriks’ group used this technique to knock out the APOB and MTTP genes in human fetal hepatocyte-derived organoids, deletions of which are responsible for two monogenic lipid disorders predisposing to NAFLD: familial hypolipoproteinemia and abetalipoproteinemia." (PMID 37175830, 2023). "Also, intestine-specific deletion of Mtp or ApoB in mice renders small and large intestines with enlarged calibers, mostly due to fat accumulation in the villus enterocytes, fully recapitulating the phenotypes reported for abetalipoproteinemia." (PMID 34236046, 2021). "The absence of functional MTP results in the degradation of nonlipidated apoB leading to abetalipoproteinemia that is characterized by the absence of plasma lipoproteins." (PMID 38325741, 2024). "Abetalipoproteinemia (ABL) and homozygous hypobetalipoproteinemia (HHBL) are syndromes resulting from the total absence or extremely low levels of apolipoprotein B. These patients present similarly during infancy with fatty diarrhea and associated fat-soluble vitamin malabsorption." (PMID 36422736, 2023).
abetalipoproteinemia (continued). "Enormous daily supplemental α-tocopherol amounts (>100 mg/kg body weight) given long-term can overcome the lack of apoB-lipoproteins in abetalipoproteinemia, to prevent neurologic disease progression and to prevent oxidative damage." (PMID 36145092, 2022). "An example of this chain of events is abetalipoproteinemia, a rare inherited disease characterized by very low/absent apolipoprotein B (Apo B)-containing particles, including chylomicrons, very low lipoprotein (VLDL) and LDL." (PMID 34198795, 2021). "Mutations in the mtp gene result in a severe reduction or complete lack of ApoB-LPs, a disease called abetalipoproteinemia." (PMID 31366908, 2019). "The presence of low density lipoproteins and apolipoprotein B in the plasma, although in decreased amounts, ruled out abetalipoproteinemia." (PMID 22104167, 2011). "Abetalipoproteinemia (ABL; OMIM 200100) is a rare monogenic disorder of lipid metabolism characterized by reduced plasma levels of total cholesterol (TC), low density lipoprotein-cholesterol (LDL-C) and almost complete absence of apolipoprotein B (apoB)." (PMID 23556456, 2013).
endothelial dysfunction (32 papers, 2011 to 2026). In vascular diseases, endothelial dysfunction is a systemic pathological state of the endothelium (the inner lining of blood vessels) and can be broadly defined as an imbalance between vasodilating and vasoconstricting substances produced by (or acting on) the endothelium. "Elevated levels of LDLs and apolipoprotein B (ApoB), which are atherogenic, contribute to lipid accumulation in the vessel wall, causing endothelial dysfunction through inflammatory response and oxidative stress." (PMID 40806126, 2025). "The ApoB/ApoA ratio is currently considered a better predictor of endothelial dysfunction, atherogenesis, and cardiovascular risk compared with cholesterol and triglycerides, especially in subjects with a normal or nearly normal lipid profile." (PMID 34901269, 2021). "Endothelial dysfunction followed by increasing infiltration and subendothelial retention of apolipoprotein B containing lipoproteins (apoB-Lps) initiates plaque buildup in arteries." (PMID 37949969, 2023). "Endothelial dysfunction results in accumulation of apolipoprotein B (apoB) and low-density lipoprotein (LDL) cholesterol in the arterial wall." (PMID 33803130, 2021). "Whenoverwhelmed with elevated plasma triglyceride levels, the apolipoprotein B48 receptormay contribute to foam cell formation, endothelial dysfunction and atherothrombogenesis." (PMID 27727360, 2016). "In addition, endothelial dysfunction parameters (Serum sVCAM-1: soluble vascular cell adhesion molecule-1, fibrinogen, and oxidized LDL), apolipoprotein A and apolipoprotein B were significantly (p < 0.001) reversed to near normal following treatment with MLE." (PMID 35893859, 2022). "Regarding the mechanism of how the high levels of LDL-C led to an increased MetS risk, previous studies suggested that the increased levels of serum apolipoprotein-B and circulating oxidized LDL might contribute to endothelial dysfunction and vascular inflammation by increasing the LDL-C levels." (PMID 34275455, 2021).
chronic kidney disease (31 papers, 2007 to 2025). Impairment of the renal function secondary to chronic kidney damage persisting for three or more months. "While the links between C4b-binding protein alpha chain and CAD are new, apolipoprotein B-100 is genetically associated with cardiovascular disease, as well as chronic kidney disease, blood pressure, and various lipids." (PMID 38129841, 2023). "More importantly, this ratio has a stronger association with CHD incidence in chronic kidney disease (CKD) patients compared with ApoB/ApoA1." (PMID 30593279, 2018). "APOB and APOA1 levels are predictors of cardiovascular events and all-cause mortality in patients with chronic kidney disease." (PMID 40787622, 2025). "Apolipoprotein A1, the key protein component of HDL, and apolipoprotein B, the major protein component of VLDL and LDL, are closely linked to chronic kidney disease (CKD)." (PMID 39860649, 2025). "Studies have found that Lp(a) had a significantly inversely correlation with the glomerular filtration rate (GFR) in patients with primary nephropathy, and ApoB/ApoA-Ι was positively correlated with the incidence of chronic kidney disease (CKD)." (PMID 34627286, 2021). "When exclusively African-ancestry studies were considered, we found that only 3 connections, between the blood pressure, lipids and chronic kidney disease phenotypes, were reproduced by one genomic region (APOB/KLHL29)." (PMID 23029515, 2012). "We designed the present case-control study in order to examine the validity of apolipoprotein (apo) A-I, B, apoB/apoA-I ratio and Lp(a) as alternative markers of cardiovascular morbidity in end-stage renal disease (ESRD) patients undergoing chronic hemodialysis (HD)." (PMID 19690648, 2007). "Several studies have identified independent associations between ApoB and LDL-C with chronic kidney disease (CKD) progression." (PMID 40379620, 2025). "Patients with chronic kidney disease (CKD) may be more susceptible to some of the potential side effects of the diet, including metabolic acidosis and the unfavorable increase in low-density lipoprotein cholesterol (LDL-C) and apolipoprotein-B (apo-B)." (PMID 38186877, 2024). "Whether serum apolipoprotein B (ApoB) is a risk factor for the development of Chronic kidney disease (CKD) has not been fully established in the general population." (PMID 37124758, 2023). "In this retrospective cohort study, a group of 258 DKD patients with stage 3–5chronic kidney disease(CKD)were divided into low ApoB (<1.1 g/L) and high ApoB (≥1.1 g/L) groups and followed-up for 20.51 ± 6.11 months." (PMID 32242489, 2020). "Chronic kidney disease, cardiovascular disease, increased serum creatinine (Scr), red blood cell count (RBC), platelets (PLT), apolipoprotein B (APOB), and decreased urine albumin to creatinine ratio (UACR) were significantly associated with lower VD and PD (all p < 0.013)." (PMID 36993806, 2023). "For example, in the Chronic Renal Insufficiency Cohort (CRIC) Study, none of the lipoproteins studied (total, LDL, HDL, VLDL, Lp(a), apoA-I, apoB) were independently associated with development of ESRD or > 50% reduction in baseline eGFR." (PMID 29929484, 2018).
coronary atherosclerosis (29 papers, 2007 to 2026). Atherosclerosis of the coronary vasculature. "Residual apoB was also calculated and remained significantly associated with the presence of coronary atherosclerosis." (PMID 41374382, 2025). "Elevated apoB are superior in assessing the residual risk of coronary atherosclerotic heart disease and severity of coronary atherosclerosis in participants with statin treatment." (PMID 35573992, 2022). "Our results suggest that elevated apoB is superior in assessing the residual risk of coronary atherosclerotic heart disease and severity of coronary atherosclerosis in patients with statin treatment." (PMID 35573992, 2022). "Our study is the first to show that concentrations of apoB are associated with the severity of coronary atherosclerosis (evaluated by syntax scores) in participants with statin treatment, but not in LDL-C." (PMID 35573992, 2022). "We next tested the association of ApoB-specific antibodies and the clinical appearance of coronary atherosclerosis." (PMID 35479271, 2022). "Higher levels of apoB were significantly associated with the severity of coronary atherosclerosis (Ptrend = 0.012)." (PMID 35573992, 2022). "Our results suggested that elevated apoB are superior in assessing residual risk of coronary atherosclerotic heart disease and severity of coronary atherosclerosis in participants with statin treatment." (PMID 35573992, 2022). "In the present study, we indirectly analyzed the association of the LDL-C/apoB ratio with the severity of coronary atherosclerosis in CAD patients with underlying DM." (PMID 28969633, 2017). "Moreover, in both NS-CAD and S-CAD, the LDL-C/apoB mean ratios were very close to the threshold value associated with an increased risk of coronary atherosclerosis, as suggested in the available literature." (PMID 41374382, 2025). "The logistic regression analysis showed consistent results, as the LDL/ApoB ratio was negatively associated with the presence of coronary atherosclerosis (B = −0.593, p = 0.010, OR 0.553, 95% CI: 0.352–0.867, R2 = 0.096); however, it showed a limited predictive power for significant CAD." (PMID 41374382, 2025). "Therefore, elevated apoB are superior in assessing residual risk of coronary atherosclerotic heart disease and severity of coronary atherosclerosis in patients with statin treatment." (PMID 35573992, 2022). "Coronary atherosclerosis is increasingly recognized as a chronic, maladaptive inflammatory disease initiated by arterial retention of apolipoprotein B (apoB)-containing lipoproteins and amplified by innate and adaptive immune responses." (PMID 42099780, 2026). "Spearman correlation analysis and generalized linear model analysis were used to assess the correlation between ApoB and the severity of coronary atherosclerosis." (PMID 41030852, 2025). "We did not register any notable differences between NS-CAD and S-CAD; however, the LDL-C/apoB ratio was lower among patients with coronary atherosclerosis." (PMID 41374382, 2025). "The objective was to determine if elevated levels of apoB is superior to LDL-C in assessing residual risk of coronary atherosclerotic heart disease and severity of coronary atherosclerosis in participants with statin treatment." (PMID 35573992, 2022). "In the Air Force/Texas Coronary Atherosclerosis Prevention Study (AFCAPS/TexCAPs), apoB concentration was significantly associated with future cardiovascular events after one year of treatment, but not LDL-C." (PMID 35573992, 2022). "Our study provides insights into the value of apoB versus LDL cholesterol in participants with statin treatment for identifying residual risk of coronary atherosclerotic heart disease and severity of coronary atherosclerosis." (PMID 35573992, 2022). "ApoB XbaI gene polymorphism ultimately leads to coronary atherosclerosis by affecting the metabolic clearance of LDL and increasing plasma ApoB levels." (PMID 32493216, 2020).